IL10 (interleukin 10)
Diseases named in the same sentence as IL10 in open-access papers (continued):
Sharing a sentence is not in itself a finding about the gene and the disease.
colitis (continued). "Our prior findings showed genetic disruption of EGFR caused earlier onset and more-severe colitis in susceptible (i.e., Il10−/−) mice." (PMID 29904166, 2018). "We compared colitis and intestinal barrier function in IL10−/− mice to mast cell deficient/IL10−/− (double knockout (DKO): KitWsh/Wsh × IL10−/−) mice." (PMID 29849494, 2018). "IL-10, which is secreted by Treg cells, is essential for intestinal homeostasis; indeed, IL-10 deficiency leads to the spontaneous development of colitis in mice." (PMID 29466999, 2018). "In IL-10 deficient mice colitis model, triptolide ameliorates post-surgical intestine inflammation by suppressing the miRNA-155/inositol polyphosphate-5-phosphatease D signaling pathway and producing of inflammatory cytokines." (PMID 29491837, 2018). "The Cdcs1 locus was first identified in the context of interleukin-10 deficient (Il10−/−) mice over 10 years ago5,8, and also controls spontaneous colitis in C57BL/6.Tbx21−/−Rag2−/− (TRUC) mice." (PMID 30228258, 2018). "IL-10-deficient mice are more susceptible to chronic colitis while IL-10-transgenic spleen cells prevent colitis induction." (PMID 29784012, 2018). "A milk-derived diet high in saturated fats, unlike a diet high in polyunsaturated fats, promotes the expansion of a sulphite-reducing pathobiont, Bilophila wadsworthia, and aggravates Th1-mediated colitis in IL-10 deficient mice." (PMID 30697218, 2018). "Utilizing mast cell-deficient × IL10-deficient (DKO) murine model of spontaneous colitis, combined with systemic mast cell engraftment approaches, the objective of this study was to define the role of the mast cell in spontaneous colitis." (PMID 29849494, 2018). "T regulatory cells also produce IL-10, which has been shown to be important in controlling inflammation, as disruption of IL-10 production caused colitis in mice." (PMID 29706961, 2018). "In fact, IL-10-deficient mice are highly susceptible to colitis, due to aberrant immune response to commensal bacteria." (PMID 30258436, 2018). "We demonstrated in this report that SCFAs, produced by gut microbiota as fermentation products of dietary fiber, promoted Th1 cell production of IL-10, thereby inhibiting colitis induced by pathogenic Th1 cells." (PMID 30177845, 2018). "Relying both on a bacterial trigger and on an immune defect, H. hepaticus-induced colitis in the context of IL-10/IL-10R axis deficiency shares many features of human inflammatory bowel diseases (IBD)." (PMID 29611556, 2018). "In contrast, adoptive transfer of iTreg cells reduces pathological scores and levels of TNF-α and IL-17 in colons of colitis mice, and IL-10-deficient mice spontaneously developed severe colitis." (PMID 30166541, 2018). "Yet another experimental model of colitis where IL-10-deficiency facilitates IL-1β proinflammatory effects comes somewhat unexpectantly from studies of TLR5-deficient mice." (PMID 30455704, 2018). "Given that intestinal permeability is a central mechanism driving intestinal inflammation in colitis models, we next assessed the impact of mast cell deficiency on intestinal barrier function in IL10−/− and DKO mice." (PMID 29849494, 2018). "For instance, maresin 1, a macrophage-derived ω-3 fatty acid metabolite, exhibited protective anti-inflammatory effects in Il10-/- (IL-10 knockout) mice, which develop colitis with iron deficiency anemia." (PMID 30469435, 2018). "Bilophila is a sulfite-reducing pathobiont and causes an interleukin-10-mediated immune response, which leads to colitis in mice." (PMID 29158587, 2017). "Another report also showed that GLP-2 alleviates the development of colitis through reducing the pro-inflammatory cytokines in IL-10-deficient mouse model." (PMID 29270177, 2017). "Under chronic intestinal inflammatory conditions including IL10−/− colitis MDR PA-association results in well-orchestrated TLR4-dependent immune responses both in intestinal and extra-intestinal compartments." (PMID 29151895, 2017).
colitis (continued). "More recently, it has been shown that celastrol ameliorates experimental colitis in IL-10 deficient mice via the upregulation of autophagy of the colon tissue cells by PI3K/Akt/mTOR signaling downregulation." (PMID 28664158, 2017). "Relying both on a bacterial trigger and on an immune defect, H. hepaticus-induced colitis in the presence of IL-10/IL-10R pathway deficiency shares many features of human IBD." (PMID 29241040, 2017). "Taken together, these data suggest that IL-10 is crucial for the anti-colitogenic function of Hsp65-LL in DSS-induced colitis and at least partially involved in the prevention of spontaneous colitis in IL-10-deficient mice." (PMID 28194152, 2017). "IL-10-deficient mice had less acute infection-associated colitis and cleared infection faster than wild-type controls, which is consistent with our results." (PMID 28935867, 2017). "In the colitis model induced by transferring cells from IL-10-deficient C57BL/6 mice to CB-17 SCID mice, elemental diet consumption prevented weight loss and suppressed intestinal inflammation, whereas mice fed standard diet showed a severe form of colitis." (PMID 29209321, 2017). "Innate immunity, in particular, plays an important role in ameliorating colitis severity, linked to IL-10 production." (PMID 28302598, 2017). "In consistency, GLP-2 treatment also reduced pro-inflammatory cytokine protein levels in the IL-10-deficient mouse model of colitis." (PMID 29270177, 2017). "In consistency with this, administration of GLP-2 led to significant improvements in animal weight loss and intestinal inflammation in IL-10-deficient mice, a spontaneous colitis mouse model." (PMID 29270177, 2017). "IL-10 plays a pivotal role in intestinal homeostasis as IL-10−/− mice spontaneously develop colitis and single-nucleotide polymorphisms in IL-10 signaling have been associated with IBD in genome-wide association studies (GWAS)." (PMID 29387056, 2017). "Results from this study showed that triggering of GPR120 by DHA treatment ameliorate the experimental colitis in IL-10 deficient mice." (PMID 28039475, 2017). "In another study, however, Nod2 was shown to rather promote colitis, given that Nod2 deficient IL-10−/− mice were protected from large intestinal inflammation." (PMID 28752081, 2017). "AMPK VilCre KO mice demonstrate exacerbated dextran sodium sulfate (DSS)-induced colitis, while metformin administration reduces colitis in interleukin-10-deficient mice as well as DSS-induced colitis in mice." (PMID 28835570, 2017). "The anti-inflammatory activity of a Lactobacillus gasseri strain-producing manganese SOD was shown to be associated with a reduction in the severity of colitis in IL-10-deficient mice." (PMID 29387056, 2017). "Previously, we showed that contrasting immune responses mediate C. jejuni induced colitis and autoimmunity in interleukin-10 (IL-10)-deficient mice, dependent upon the infecting strain." (PMID 28789710, 2017). "C. jejuni 11168 infected C57BL/6 genetically wild-type and IL-10−/− were used as gastroenteritis controls, due to their well-characterized reputation as colitis resistant (wild-type) and colitis susceptible (IL-10−/−)." (PMID 28789710, 2017). "Experimentally, intracolonic administration of CHR reduced colitis severity through the production of IL-10 and arginase activities and the promotion of AAM-associated gene expression (Ym1, Fizz1) in the colonic mucosa and peritoneal macrophages." (PMID 28951733, 2017). "Consistent with this, dietary histidine ameliorated colitis in an IL-10-deficient (IL-10−/−) cell transfer model of Crohn’s disease, by regulation of NF-κB activation, and subsequent inhibition of proinflammatory cytokine production by macrophages." (PMID 28832517, 2017). "We reported previously that Nlrp3−/− mice were more susceptible to colitis and exhibited reduced colonic IL-10 expression." (PMID 27610005, 2016).
colitis (continued). "IL-10-deficient mice develop severe colitis, accompanied by tissue damage and excessive inflammation." (PMID 27683580, 2016). "Gut microbiota of IL-10 deficient mice developing spontaneously severe colitis have decreases in bacterial diversity and increases in the occupancy of Enterobacteriaceae." (PMID 27350830, 2016). "Patients with mutations in IL10 or IL10 receptor (IL10R) genes present with severe colitis, perianal disease and folliculitis manifesting in the first months of life." (PMID 26822028, 2016). "Two independent reports show that treatment with FTY20 significantly attenuates the development of colitis induced by DSS or due to genetic deficiency of IL-10." (PMID 27656050, 2016). "Very early-onset colitis and perianal disease leading to fistula formation suggested probability of inherited deficiencies of IL-10 or IL-10 receptor." (PMID 27699073, 2016). "This idea is also corroborated by various animal models in which either loss of IL-10 induces spontaneous colitis or application of IL-10 ameliorates disease symptoms." (PMID 27491073, 2016). "A. parvulum induces pancolitis in colitis-susceptible interleukin-10-deficient mice and this phenotype requires the presence of the intestinal microbiota." (PMID 27876802, 2016). "Animal model: spontaneous development of colitis in IL-10–deficient mice or in T and B cell–deficient mice upon transfer of antigen-experienced T cells." (PMID 27101372, 2016). "Enhanced phosphorylated levels of RAF was observed in the IL-10 deficient mice (which develop spontaneous colitis over time) during active disease." (PMID 27997590, 2016). "The spontaneous onset of colitis in response to commensal gut flora in IL-10–deficient mice and enhanced susceptibility of IL-10–deficient mice to septic shock demonstrate the importance of IL-10 as a negative feedback regulator in the immune system." (PMID 27549173, 2016). "Loss of diversity in the GI microbiota has been reported in patients with IBD and in animal models of colitis such as IL10-deficient mice, as well as in several strains of immunodeficient mice." (PMID 26950850, 2016). "In humans, IL-10 appears to play an important protective role in infants, with altered IL-10 levels associated with inflammatory conditions such as bronchopulmonary dysplasia, sepsis, seizures, and colitis." (PMID 27737696, 2016). "It has been recently demonstrated that SEW 2871, another selective S1P1 agonist, ameliorates colitis in IL-10-deficient mice, by reducing proinflammatory cytokines production and promoting the expression of TJ typical proteins." (PMID 26880864, 2016). "In IL10-deficient or IL10 receptor-deficient mice, the animals develop severe colitis pathology following microbial colonization of the gut, strongly arguing for a regulatory role of IL10 in the gut." (PMID 27014275, 2016). "After six weeks, mice that had received either WT or IL-10 KO Treg-of-B cells exhibited less weight loss, milder histopathology, and milder colitis features compared with mice that only received colitogenic T cells." (PMID 27581189, 2016). "IL10 deficient mice develop spontaneous colitis, suggesting the important roles of IL10 in regulating overactive inflammatory responses." (PMID 27807812, 2016). "The findings of the present study revealed that Lcn2 prevents the development of spontaneous colitis in IL-10 deficient mice by enhancing phagocytic bacterial clearance in macrophages." (PMID 27734904, 2016). "This perception is also based on the observation that inactivation of STAT3 in neutrophils and macrophages causes chronic murine colitis via increased Th1 responses and decreased signal transmission of IL-10." (PMID 26938566, 2016). "Loss of function of IL-10 and IL-10R molecules causes refractory colitis with folliculitis and perianal disease, manifesting very early in infancy." (PMID 26822028, 2016). "Further, strains of L. plantarum have been shown to ameliorate colitis also in IL-10-deficient mice." (PMID 27462316, 2016).
colitis (continued). "Gut microbial profiling of germ-free IL-10-deficient mice that develop spontaneous colitis revealed that intestinal inflammation induces changes in the composition of the microbiota with an overgrowth of Enterobacteria." (PMID 25759839, 2015). "A key suppressor of macrophage-associated inflammation is the IL-10/IL-10 receptor (IL-10R) axis, as mice bearing mutations in IL10-Ra in intestinal CX3CR1+ macrophages developed severe colitis comparable to the pathology reported for IL-10-deficient animals." (PMID 26082775, 2015). "On the other hand, a recent study suggests that macrophages are a prime cell target for IL-10 activity in the gut in that loss of Il-10ra specifically on macrophages resulted in spontaneous colitis development." (PMID 25944983, 2015). "The main of the IL-10 pathway within the colonic mucosa is confirmed by the occurrence of severe colitis during the first weeks of life in infants carrying mutations in IL10, IL10RA, or IL10RB genes." (PMID 26579126, 2015). "The spontaneous development of colitis in IL-10 deficient mice shows the relevance of this cytokine in controlling the immune response to commensal flora of the gut." (PMID 25853847, 2015). "IL-10 is an important anti-inflammatory cytokine that can be secreted by Treg cells, and IL-10 defects cause spontaneous colitis in mice." (PMID 26347453, 2015). "It was also reported that the presence of Helicobacter hepaticus, a species of commensal bacteria, exacerbated colitis in IL-10-deficient mice." (PMID 25420450, 2015). "For example, inoculation with a simple consortium of seven human-derived IBD-related intestinal bacteria has been shown to induce colitis in germ-free interleukin-10 gene-deficient (Il10-/-) mice." (PMID 25768951, 2015). "In line, mice that develop spontaneous colitis due to IL-10 deficiency have increased disease severity when the actions of 5-HT are amplified by genetic deletion of the serotonin transporter SERT." (PMID 26635804, 2015). "Local delivery of IL-10, through intracolonic administration of an adenovirus expressing IL-10 was able to reduce colitis in IL-10-deficient mice." (PMID 25889561, 2015). "The mice treated with CCX025 also had increased colonic levels of the anti-inflammatory cytokine IL-10, in concordance with the fact that IL-10−/− mice have a predisposition to develop colonic inflammation." (PMID 26457007, 2015). "It is well known that different commensal bacteria induce distinct types of colitis in IL-10-deficient mice." (PMID 25420450, 2015). "ACE inhibitor treatment was also effective in spontaneous colitis of IL-10-deficient mice and this finding has been confirmed by other studies." (PMID 24678903, 2014). "When treated with AOM, Il10-/- mice were found to show an increased risk of colon tumor development, spontaneous colitis, and CRC, while AOM-WT mice were devoid of colitis and rarely progressed to adenomas." (PMID 25076949, 2014). "Our findings highlighted that the eIF2α phosphorylation was altered in both UC patients and IL10/Nox1dKO mice (this study) prior to colitis associated with an increased formation of the GADD34 and PP1c/GADD34 complex." (PMID 25014110, 2014). "IL-10-deficient mice spontaneously develop colitis, suggesting that IL-10 exerts in vivo immunoregulatory effects largely in the intestinal tract." (PMID 27574641, 2014). "IL-23p19-deficient mice develop severe colitis in IL-10 deficient mice and IL-12p35 deficient mice develop a mild colitis." (PMID 25295619, 2014). "This diet led to a higher incidence of colitis in genetically susceptible IL-10−/− mice as well as in dextran sulfate sodium -induced colitis." (PMID 25309544, 2014). "First indications for this came from early observations in IL-10-deficient mice that developed spontaneous colitis under conventional housing conditions which was significantly less severe (or even absent) when mice were held under SPF conditions." (PMID 24489792, 2014).
colitis (continued). "The activation of STAT3, which plays an important role in the inflammatory response, in intestinal epithelial cells and myeloid cells promotes the development of colitis-associated cancer and influences the anti-inflammatory effects of IL-10." (PMID 25286337, 2014). "The variation of neutrophil numbers in the distal colon of IL10−/− was strongly associated (r = 0.82, p<0.0001) with histological scores in the distal colon, which showed high heterogeneity (total colitis score from 0.6 to 8.8)." (PMID 24849654, 2014). "This study investigates the safety and therapeutic benefit of a locally administered lentiviral vector encoding murine interleukin-10 in altering the onset and relapse of dextran sodium sulfate induced murine colitis." (PMID 24712338, 2014). "IL-10 deficient mice were also found to be resistant to spontaneous colitis when kept in germ-free environment." (PMID 24616886, 2014). "Deliberate infection of SPF-housed IL-10−/− mice with H. hepaticus significantly exacerbated the development of colitis, and susceptibility to colitis induction is re-established in WT mice, treated with anti-IL-10R mAb following H. hepaticus infection." (PMID 24489792, 2014). "In turn, studies have also shown that chemical-induced colitis or spontaneous colitis associated with an IL-10 deficiency is increased in severity when coupled with the 5-HT enhancing effects of a knockout of SERT." (PMID 25565996, 2014). "The importance of IL-10 for regulating immunity is highlighted by the observation that IL-10 deficiency or blockade causes the early development of colitis in mice." (PMID 25352846, 2014). "The susceptibility to H. hepaticus-induced colitis differed considerably between Il10−/− mice originating from the two institutions." (PMID 23951007, 2013). "Mice deficient in IL-10 develop colitis spontaneously, and low levels of IL-10 are positively correlated with recurrences of Crohn's disease." (PMID 23874391, 2013). "The IL-10−/− mouse model of colitis is initiated by loss of T cell immunosuppression that is exacerbated by commensal microflora and intestinal barrier dysfunction." (PMID 24244444, 2013). "sEH inhibitors attenuate the chronic colitis associated with IL-10 knockout in mice, indicating that epoxygenases are protective at least in animal models of bowel inflammation." (PMID 24058654, 2013). "The inhibitory effects of CLA in colitis of IL-10-deficient mice were also associated with expansion of CD4+CD25+Foxp3+ regulatory T cells (Tregs)." (PMID 23730302, 2013). "With regards to this shared locus, Cdcs1 on chromosome 3 was first noted in a QTL study of spontaneous colitis using IL10 deficient mice." (PMID 23442222, 2013). "IL-10−/− mice which had moderate colitis and only slight goblet cell loss had significantly diminished guanylin mRNA levels." (PMID 24244444, 2013). "IL-10 deficient mice develop spontaneous colitis and show exaggerated inflammatory responses to infection, while deficiencies in IL-10 production or mutations in the IL-10 receptor result in inflammatory diseases in men." (PMID 23951138, 2013). "Contradictory data was seen in IL-10 deficient (IL-10−/−) mice, showing that IL-10−/− mice fail to develop spontaneous colitis if reared in germ-free conditions." (PMID 24325678, 2013). "Previous studies from our laboratory showed that CLA ameliorated intestinal tissue damage in IL-10-deficient mice and colitis induced by dextran sodium sulfate (DSS)." (PMID 23730302, 2013). "In vitro studies indicate that guanylin production is specifically and profoundly diminished by TNFα and this is consistent with the loss of guanylin expression IL-10−/− colitis." (PMID 24244444, 2013). "This study examined the effect of several current CD treatments, including HC, EEN, MNZ, and a combination of EEN and MNZ, on the intestinal barrier using an H. trogontum infected IL-10 gene-deficient mouse model of colitis." (PMID 24027765, 2013).